PCSK9 (proprotein convertase subtilisin/kexin type 9)
Diseases named in the same sentence as PCSK9 in open-access papers (continued):
Sharing a sentence is not in itself a finding about the gene and the disease.
Obesity (78 papers, 2012 to 2025). Accumulation of substantial excess body fat. "Another study has shown a distinct structural similarity between the C-terminus cysteine-rich domain (CRD) of PCSK9 and the resistin homotrimer, a pro-inflammatory factor associated with obesity." (PMID 40076547, 2025). "Data from Literature report that obesity upregulates PCSK9 expression which positively correlates with body mass index and high levels of PCSK9 expression are associated with disease progression." (PMID 39940773, 2025). "Previous observational studies have shown that obesity is associated with elevated serum PCSK9 levels, and rising circulating PCSK9 levels have been linked to a reduced response to PCSK9 inhibitors." (PMID 40089775, 2025). "On the other hand, increased levels of the circulating proconvertase subtilisin-kexin 9 (PCSK9) are found in patients with type 2 diabetes, obesity and CVD and are associated with CVD severity." (PMID 38532033, 2024). "In our study, cord blood PCSK9 concentration was significantly associated with maternal overweight/obesity status, after adjusting for GA, birth weight, sex, and intrauterine growth restriction." (PMID 38440108, 2024). "The authors revealed the link between the rs2483205 polymorphism of the PCSK9 gene and an elevated risk of obesity." (PMID 36980866, 2023). "Recent study reported that PCSK9 was positively correlated with BMI in women and obesity was associated with elevated PCSK9 levels." (PMID 35498417, 2022). "With obesity and cardiovascular disease as main causes of death worldwide, a safe, effective and permanent therapy to inhibit PCSK9 can improve health span and quality of life." (PMID 34731223, 2021). "Studies have identified that obesity upregulates the expression of PCSK9 and high levels of PCSK9 are again associated with a progression of the disease, therefore making it a vicious feedback cycle between adiposity and PCSK9." (PMID 34356856, 2021). "This extends prior smaller studies where PCSK9 has been positively associated with obesity cross-sectionally, and is particularly notable in light of the known role of PCSK9 levels in LDL cholesterol metabolism and atherosclerosis development." (PMID 32404980, 2020). "Furthermore, two studies observed a direct association between the increase in PCSK9 levels and obesity." (PMID 39459005, 2024). "In multivariate linear regression analysis, higher cord plasma PCSK9 concentration was significantly associated with maternal overweight/obesity status (b = 50.12; 95% CI, 4.02-96.22; P = .033), after adjusting for gestational age, birth weight, male sex, and intrauterine growth restriction." (PMID 38440108, 2024). "To conclude, PCSK9 gene polymorphisms might be a promising trait to evaluate in future genetic studies of obesity among psoriatic patients." (PMID 36980866, 2023). "Recent data imply that PCSK9 gene polymorphisms might be another possible link between psoriasis and obesity." (PMID 36980866, 2023). "Modification of obesity-related cardiovascular risk factors is essential for reducing the risk of atherosclerotic disease and PCSK9-targeting therapy may be important in such metabolic disorders." (PMID 36077166, 2022). "In addition, loss of PCSK9 has also been shown to result in hepatic injury in mice with diet-induced obesity, an effect largely attributed to the effects of PCSK9 on its target CD36." (PMID 33643060, 2021). "Therefore, we hypothesize that rs2483205 may decrease CAD risk by modulating gene transcription and affecting TC levels, and it may be involved in adipogenesis by affecting PCSK9 levels, which enhances the risk of obesity." (PMID 34075144, 2021). "In line with the previous reports, we found PCSK9 was positively correlated with both BMI and waist circumference in females, suggesting that PCSK9 may be associated with obesity, especially visceral adiposity, the most prevalent features of the cardiovascular disease." (PMID 34041285, 2021).
Obesity (continued). "Interestingly, there have been some case reports of individuals with PCSK9 loss-of-function (LOF) mutations that were associated with liver steatosis in the context of obesity and type 2 diabetes; however, individuals with LOF and hypocholesteremia do not exhibit excessive liver fat accumulation." (PMID 31748600, 2019). "PCSK9 levels in obesity have been shown upregulated and VSMC can synthesize a significant amount of this protein." (PMID 39940773, 2025). "Although some studies suggest that PCSK9 and APOA5 are positively associated with comorbid depression and obesity, reproducible associations with depressive symptoms are limited, given their strong metabolic effects." (PMID 41375608, 2025). "Particularly, leptin, resistin, and PCSK9 demonstrated obvious decreases compared to the Fat only group, indicating FIP-fve’s ability to ameliorate obesity-associated metabolic and inflammatory alterations." (PMID 40998975, 2025). "We conclude that PCSK9 may be a useful biomarker of lipoprotein metabolism in fetal life because PCSK9 levels in the neonatal-placental circulation are susceptible to several conditions that affect lipoprotein regulation including maternal overweight status/obesity." (PMID 38440108, 2024). "PCSK9’s role in LDL receptor degradation correlates with heightened PCSK9 levels in obesity, while TGF-β1 induces PCSK9 secretion." (PMID 38762465, 2024). "PCSK9 levels can be modified by many factors, among which, diet, obesity and metabolic diseases are the most important." (PMID 37004042, 2023). "Cardiovascular and obesity studies demonstrate that elevated circulating Cer can be decreased using cholesterol-lowering drugs (statins and PCSK9 inhibitors) and exercise." (PMID 37853018, 2023). "To this end we demonstrate that ME improved hepatic lipid homeostasis, attenuated obesity and improved atherogenic serum parameters in a PCSK9-dependent manner." (PMID 37242292, 2023). "Clinical data showed that cilostazol treatment significantly reduced serum PCSK9 levels in patients with obesity." (PMID 36077166, 2022). "The obesity-dependent effects of cilostazol on PCSK9 expression observed from bench to bedside demonstrates the therapeutic potential of cilostazol in clinical settings." (PMID 36077166, 2022). "To define the role of PCSK9 in obesity in vivo, we fed mice high-fat chow for 16 weeks, which produced obesity and hyperglycemia." (PMID 36558473, 2022). "For instance, an interesting study recently reported that the link between HOMA-IR and the level of PCSK9 is evident in people with obesity." (PMID 36387872, 2022). "In the following, we will summarize studies that have analyzed PCSK9 levels and lipoproteins in patients and experimental models suffering from metabolic disorders, including diabetes, obesity as well as inflammation and chronic liver injury." (PMID 35162992, 2022). "In a study on non-diabetic individuals (n=79), overweight individuals (n= 32), and individuals with obesity (n= 10), the plasma apoM levels were inversely correlated with BMI, and the PCSK9 levels were positively correlated with insulin levels." (PMID 34093440, 2021). "In order to integrate our data into the physiological context and to get an idea of which PCSK9 quantities play a role under pathological conditions in vivo, we investigated changes in PCSK9 release and expression in mice with diet-induced obesity." (PMID 33643060, 2021). "We review a number of kinetic studies investigating the role of PCSK9 in lipoprotein metabolism in humans including healthy individuals, subjects with GOF and LOF mutations in PCSK9, as well as in patients with obesity and elevated Lp(a)." (PMID 33643062, 2021).
Obesity (continued). "The levels of PCSK9 expression in adipose tissue positively correlates with the body mass index (BMI) of the individual, suggesting that obesity and adiposity induces the expression of PCSK9." (PMID 34356856, 2021). "To better mimic the type of diet that causes obesity, we fed mice a high-fat diet (~60% fat chow) for 8 weeks, and measured their weight, plasma LDL, and PCSK9 biweekly." (PMID 34731223, 2021). "A number of studies addressed the potential role of PCSK9 in systemic metabolism, obesity, and other CMDs." (PMID 32225075, 2020). "In this study, the major goal was to determine if human leptin played a role in regulating the uptake of LDL by PCSK9 in hepG2 cells for the sake of exploring the potential links of leptin with PCSK9 in obesity." (PMID 27663646, 2016). "Previous studies have suggested that people with obesity showed elevated serum levels of leptin as well as lipid dysfunction and proprotein convertase subtilisin/kexin type 9 (PCSK9) played an important role in the regulation of lipid metabolism recently." (PMID 27663646, 2016). "As T1D is increasingly associated with insulin resistance and obesity the investigation of these two parameters, EAT volume and PCSK9 concentration, in this setting, could add new information in this population." (PMID 38532033, 2024). "Additionally, insulin resistance plays a crucial role in the homeostasis of PCSK9 in severe obesity." (PMID 38115042, 2023). "PCSK9, MST1, and RPS6K1 predominantly mediated the detrimental effect of sedentary behavior on CAD, while the effect of smoking was mainly mediated by RGMB, PCSK9, ITPKA, RPS6KA1, and AGER, which partially aligned with the observed association pattern between obesity and CAD." (PMID 38049831, 2023). "It would be important to elucidate which hepatic lipids are mostly affected by PCSK9 in obesity." (PMID 37004042, 2023). "Higher BMI score was associated with higher levels of PCSK9 in a Sub-Saharan African Population of Patients with Obesity, a finding that was not also observed in the current study." (PMID 35893257, 2022). "Despite the obesity-dependent effects of cilostazol on PCSK9 expression, we observed similar effects on the expression of AMPKα and PPARγ, suggesting that mechanisms beyond AMPK/PPARγ activation may be at play." (PMID 36077166, 2022). "But more recent metabolic studies indicate that PCSK9 inhibitors may enhance the clearance of triglyceride rich postprandial lipoproteins in obesity." (PMID 35320320, 2022). "Lastly, likely, the surprising results regarding the increase in PCSK9 levels with RIF may be because the study population was mainly people with obesity." (PMID 35454343, 2022). "Interestingly, diverse effects of cilostazol on PCSK9 expression were observed between obesity and non-obesity from bench (in vitro and in vivo) to bedside." (PMID 36077166, 2022). "Our data suggest a similar effect in mice with diet-induced obesity: While juvenile mice showed a strong increase of liver and fat PCSK9 protein expression, at higher age adipose tissue might contribute to plasma PCSK9." (PMID 33643060, 2021). "Therefore, we also analyzed adipose tissue PCSK9 mRNA and protein expression in those mice with diet-induced obesity." (PMID 33643060, 2021). "The function of PCSK9 in relation to obesity seems controversial." (PMID 34356856, 2021). "Similarly, our analyses in mice with diet-induced obesity demonstrate an increase of PCSK9 plasma levels from 100 ng/ml (control animals) to up to 350 ng/ml (HFD animals)." (PMID 33643060, 2021).
Obesity (continued). "Validating the hypothesis that PCSK9 provides a defence mechanism against obesity, studies showed that visceral adipose tissue content increases in PCSK9 knockout mice due to increased expression of VLDLR." (PMID 34356856, 2021). "However, with increasing rates of sedentary behaviors and obesity, it is likely that statins and/or PCSK9 inhibitors would be potential pharmaceutical interventions for the overall pediatric population since the safety profiles of these interventions are not well documented in long-term studies." (PMID 37904165, 2023). "Besides the PCSK9 genotype and other contributing gene variations, fat distribution, obesity, insulin sensitivity and gender may be further confounding factors." (PMID 35162992, 2022). "Also, studies in adults coupled with studies in cells and mice indicated that hyperinsulinemia in obesity/T2DM might upregulate PCSK9 expression." (PMID 35498417, 2022). "Furthermore, liraglutide is a glucagon-like peptide-1 (GLP-1) receptor agonist that has been used clinically as anti-diabetic and anti-obesity treatment, which has also been identified as a potent suppressor of PCSK9 expression, explaining at least partly its beneficial effect on CVDs." (PMID 34356856, 2021). "Furthermore, evidence from small-scale research (aged 15–26 years) found that obesity and type 2 diabetes were associated with significantly higher levels of PCSK9 in America young women, but not in young men." (PMID 34041285, 2021). "This study aims to assess the impact of statins or PCSK9 inhibitors on AHR and lung fibrosis in an HFD-induced obesity model of mouse." (PMID 38762465, 2024). "The detrimental effect of obesity on CAD appears to be primarily mediated by MAP1LC3A, ANGPTL4, RPS6KA1, PCSK9, ITPKA, and AGER." (PMID 38049831, 2023). "To further examine the correlation between PCSK9 and the metabolic profile observed in mice fed HFD, we also utilized a model of diet-induced obesity in PCSK9−/− mice." (PMID 37242292, 2023). "On the contrary, PCSK9 also influences the expression of receptors and molecules other than VLDLR to promote obesity." (PMID 34356856, 2021). "The apoM levels correlated positively with PCSK9 levels in lean individuals (r= 0.337, P= 0.041) after adjustment for BMI and apoB, but not in individuals who were overweight or had obesity, suggesting that LDL-associated apoM may be differently processed depending on metabolic health." (PMID 34093440, 2021). "PCSK9 (TG, HDL cholesterol, ApoB and ApoA1/ApoB) was shown interactions with overweight/obesity to influence serum lipid levels." (PMID 26744084, 2016). "HFD led to greater body weight, serum cholesterol, glucose, and elevated levels of pro-inflammatory cytokines and adipokines, such as leptin, resistin, PCSK9, and DPPIV/CD26, consistent with findings that obesity drives chronic inflammation and metabolic dysregulation." (PMID 40998975, 2025). "Amongst other genes that link depression with obesity, melanin-concentrating hormone receptor 2 (MCHR2), proprotein convertase subtilisin/kexin type 9 (PCSK9), and apolipoprotein A5 (APOA5) may be mentioned, as genes involved in energy-related processes." (PMID 41375608, 2025). "There is a lack of research on the effects of dietary fat on PCSK9, and liver steatosis without obesity in a single experiment, particularly in rats." (PMID 39354056, 2024). "In our study we also found a relationship between increased levels of PCSK9 in patients with high WC, but not with overweight and obesity." (PMID 38532033, 2024).
Obesity (continued). "On the contrary, the relative abundance of PCSK9 and NLRP3 positively correlated with obesity diagnosis indices (body weight, fat mass and Lee’s index), abnormal sperm rate, pyroptosis markers including Caspase-1, GSDMD, IL-1, IL-18 and the level of lipid metabolizing hormone (TG, TC and LDL)." (PMID 37935689, 2023). "For example, physiologic dissection of the actions of soluble proteins such as proprotein convertase subtilisin/kexin type 9 (PCSK9) and glucagon-like peptide 1 (GLP1) have yielded among the most promising therapeutics to treat cardiovascular disease and obesity, respectively." (PMID 37214953, 2023). "The significant association between plasma PCSK9 and LDL-apoB was independent of age, obesity status, homeostasis model assessment (HOMA) score and energy intake." (PMID 33643062, 2021). "The SNPs of ABCA-1 (LDL-C and ApoA1/ApoB); LIPC (TC, LDL-C, ApoA1 and ApoB); LIPG (ApoB); MTHFR (TC, TG and LDL-C); MYLIP (TC and TG); PCSK9 (TG, HDL-C, ApoB and ApoA1/ApoB); PPARD (TG and ApoA1/ApoB); and SCARB1 (TG, ApoA1 and ApoB) interacted with overweight/obesity to modulate serum lipid levels." (PMID 23039238, 2012). "Neonates born to mothers with overweight/obesity have higher cord blood PCSK9 concentrations compared with the nonoverweight/nonobese group, and higher cord blood PCSK9 concentrations were significantly associated with maternal overweight/obesity status, after adjusting for perinatal factors." (PMID 38440108, 2024). "The findings regarding the diverse effects of cilostazol on PCSK9 expression between obese and non-obese conditions (in vitro, in vivo, or clinically) are novel, suggesting another mechanisms of action are responsible for the anti-atherosclerotic effects of cilostazol for obesity." (PMID 36077166, 2022).